RNU6-324P (RNA, U6 small nuclear 324, pseudogene)
Gene: Small nuclear RNA gene on chromosome 18 (12,098,427 to 12,098,532, forward strand). Ensembl gene ENSG00000200827.
Homologues: Orthologues: chimpanzee U6 (98% identical), macaque U6 (89% identical). Paralogues in human: RNU6-819P (86% identical), RNU6-1251P (85% identical), RNU6-247P (85% identical), RNU6-653P (85% identical), RNU6-1263P (84% identical), RNU6-16P (84% identical), RNU6-38P (84% identical), RNU6-480P (84% identical), RNU6-1 (83% identical), RNU6-1021P (83% identical), RNU6-1103P (83% identical), RNU6-11P (83% identical), and 1289 more.